ZNF473 (zinc finger protein 473)
Description:
Involved in histone 3'-end pre-mRNA processing by associating with U7 snRNP and interacting with SLBP/pre-mRNA complex. Increases histone 3'-end pre-mRNA processing but has no effect on U7 snRNP levels, when overexpressed. Required for cell cycle progression from G1 to S phases.
Synonyms: KIAA1141; ZFP100; DKFZP434N043; HZFP100; ZN473
Tractability: PROTAC: UniProt records ubiquitination sites on it; ubiquitination databases record sites on it.
Gene: Protein-coding gene on chromosome 19 (50,025,714 to 50,053,414, forward strand). Ensembl gene ENSG00000142528.
Subcellular location: Nucleus
Subcellular location (Human Protein Atlas): Nucleoplasm
Pathways (Reactome):
Gene expression (Transcription): Generic Transcription Pathway; RNA Polymerase II Transcription Termination
Metabolism of RNA: SLBP Dependent Processing of Replication-Dependent Histone Pre-mRNAs; SLBP independent Processing of Histone Pre-mRNAs
Gene Ontology:
Molecular function: protein binding; transcription cis-regulatory region binding
Biological process: mRNA 3'-end processing by stem-loop binding and cleavage; negative regulation of transcription by RNA polymerase II; regulation of DNA-templated transcription
Cellular component: Cajal body; nucleoplasm; nucleus
Genetic constraint (gnomAD): Loss-of-function variants: 4 observed, 11.28 expected, observed/expected ratio (o/e) 0.35, 90% interval 0.17 to 0.81. The upper end of that interval is the gene's LOEUF score, 0.81, which puts it in group 3 of 6, group 1 being the genes least tolerant of losing a copy. Missense variants: 854 observed, 1,140.6 expected, observed/expected ratio (o/e) 0.75, 90% interval 0.71 to 0.79. Synonymous variants: 404 observed, 412.79 expected, observed/expected ratio (o/e) 0.98, 90% interval 0.9 to 1.06.
Homologues: Orthologues: chimpanzee ZNF473 (98% identical), macaque ZNF473 (93% identical), dog ZNF473 (65% identical), pig ZNF473 (64% identical), guinea pig ZNF473 (55% identical), rat Zfp473 (55% identical), mouse Zfp473 (51% identical), Drosophila melanogaster mld (13% identical), zebrafish zgc:66472 (12% identical). Paralogues in human: ZNF91 (38% identical), ZNF160 (36% identical), ZNF184 (35% identical), ZNF208 (35% identical), ZNF420 (35% identical), ZNF107 (35% identical), ZNF729 (34% identical), ZNF347 (33% identical), ZNF594 (33% identical), ZNF99 (33% identical), ZNF84 (33% identical), ZNF845 (31% identical), and 24 more.
Diseases named in the same sentence as ZNF473 in open-access papers:
ZNF473 is named in the same sentence as 8 diseases in open-access papers, as found by Europe PMC text mining. Sharing a sentence is not in itself a finding about the gene and the disease. The quoted sentences say what the papers report.
cervical cancer (1 paper, 2017). A primary or metastatic malignant neoplasm involving the cervix. "ZNF473 has not been described to be associated with cervical cancer." (PMID 29312619, 2017).
congenital lung malformations (1 paper, 2021). "Noticeably, the lncRNA FLJ26850 might be linked to congenital lung malformations via the ZNF473-mediated biological process." (PMID 34844556, 2021). "Finally, we identified the lncRNA FLJ26850 might be related to congenital lung malformations via ZNF473." (PMID 34844556, 2021). "The lncRNA FLJ26850 might be related to congenital lung malformations via ZNF473." (PMID 34844556, 2021).
germ cell tumor (1 paper, 2022). A benign or malignant, gonadal or extragonadal neoplasm that originates from germ cells. "Wehave experimentally confirmed a decrease in the transcription level of twoselected genes (ZBTB32 and ZNF473) in germ cell tumors." (PMID 36348719, 2022). "In germ-cell tumors, ZBTB32 transcription is suppressed to an almostundetectable level,while ZNF473 transcription is decreased to thevalues characteristic of other tissues." (PMID 36348719, 2022). "The samples of normal tissues adjacent to germ cell tumors are characterized bya large spread in the ZBTB32 and ZNF473 transcription levels from values closeto those in the control samples (samples 5N, 8N, and 14N) to onescharacteristic of tumors (samples 7N and 21N)." (PMID 36348719, 2022).
cancer (4 papers, 2012 to 2026). A tumor composed of atypical neoplastic, often pleomorphic cells that invade other tissues. "ZNF473 has been reported as a diagnostic marker in various cancers." (PMID 39764438, 2024). "The proper dosage and splicing of cell cycle genes is critical for cell growth and the prevention of cancer, highlighting the importance of ZNF473 in human health and disease." (PMID 39303722, 2024).
tumor (3 papers, 2022 to 2026). "Analyses based on the Tumor-Immune System Interaction Database indicated that ZNF473 expression correlated with both molecular and immune subtypes in multiple cancers." (PMID 42222414, 2026). "In general, a significant decrease in the ZNF473 and ZBTB32 transcriptionlevels is observed in tumor as compared to healthy tissue (theMann–Whitney p-value is < 0.02 in both cases and >0.4 in ZNF446).These genes can act as markers for germ cell-derived tumors." (PMID 36348719, 2022).
ZNF473 also shares sentences with these, for which no sentence is quoted: colorectal cancer (1 paper); hepatocellular carcinoma (1); testicular germ cell tumor (1).